CDY1 (chromodomain Y-linked 1)
Description:
Has histone acetyltransferase activity, with a preference for histone H4.
Synonyms: CDY1A; CDY
Tractability: Small molecule: a high-quality ligand is known; it has a high-quality binding pocket. PROTAC: a small molecule that binds it is known.
Target class: Epigenetic regulator; Reader; Methyl-lysine/arginine binding protein; Chromodomain
Gene: Protein-coding gene on chromosome Y (25,622,117 to 25,624,902, forward strand). Ensembl gene ENSG00000172288.
Subcellular location: Nucleus
Gene Ontology:
Molecular function: histone H3K27me3 reader activity; histone H3K9me2/3 reader activity; transcription corepressor activity; protein-lysine-acetyltransferase activity
Biological process: negative regulation of peptidyl-lysine crotonylation; spermatogenesis; chromatin organization; negative regulation of DNA-templated transcription
Cellular component: nucleus
Homologues: Orthologues: macaque CDY (80% identical), mouse Cdyl (59% identical), zebrafish cdyl (45% identical), rat AABR07039112.1 (40% identical), Caenorhabditis elegans B0272.4 (12% identical), Drosophila melanogaster Dci (11% identical), Drosophila melanogaster CG8778 (10% identical), Drosophila melanogaster Srlp (10% identical), Caenorhabditis elegans ech-5 (9% identical), Drosophila melanogaster CG14787 (9% identical), Drosophila melanogaster HIPP1 (8% identical), Caenorhabditis elegans ech-3 (8% identical), and 1 more. Paralogues in human: CDY1B (96% identical), CDY2A (94% identical), CDY2B (94% identical), CDYL (60% identical), CDYL2 (37% identical), ECHS1 (13% identical), ECHDC3 (12% identical), ECHDC2 (12% identical), HIBCH (11% identical), ECH1 (11% identical), AUH (11% identical), ECHDC1 (9% identical), and 1 more.
Diseases named in the same sentence as CDY1 in open-access papers:
CDY1 is named in the same sentence as 8 diseases in open-access papers, as found by Europe PMC text mining. Sharing a sentence is not in itself a finding about the gene and the disease. The quoted sentences say what the papers report.
Azoospermia (8 papers, 2014 to 2022). Absence of any measurable level of sperm,whereby spermatozoa cannot be observed even after centrifugation of the semen pellet. "In a similar study concomitant deletion of both DAZ and CDY1 copies in males predisposes them to azoospermia or severe oligozoospermia deletion of CDY1b copy alone is also reported to be associated with oligo/azoospermia." (PMID 29454353, 2018). "We conducted the research to further confirm CDY1 gene as a counseling biomarker for doctors treating azoospermia-related infertility and for patients to avoid undergoing unnecessary testicular sperm extraction." (PMID 27525321, 2016). "DAZ, CDY1, BPY2, and PRY are some genes located in AZFc which can be directly related to the incidence of oligozoospermia and azoospermia." (PMID 34983649, 2022). "CNVs of DAZ, CDY1, and BPY2 are correlated with decreased total motile sperm count and lead to azoospermia and moderate/severe oligozoospermia phenotypes." (PMID 34983649, 2022). "Two candidate genes, DAZ - deleted in azoospermia (DAZ; 400003), and CDY1 – chromodomain Y (CDY1; 400016) in the AZFc region are critical and required for spermatogenesis and their associations with male infertility are well-studied." (PMID 31000748, 2019). "Based on copy number estimates of DAZ and CDY1 genes, it is observed that only those men with two DAZ and one CDY1 copy deleted will have azoospermia or oligozoospermia, retention of any one of these genes will be almost always be associated with normozoospermia." (PMID 29454353, 2018).
Infertility (5 papers, 2010 to 2021). "Interestingly, we identified AZFc partial deletions (gr/gr, b1/b3, b2/b3, b3/b4) in a total of 127 infertile men that accounted for 13.1%, with the impact of different DAZ and CDY1 copies deletions and their associations leading to spermatogenic failure and male infertility." (PMID 31000748, 2019). "Three patients and three reference men carried a secondary b2/b4 duplication adding one or more amplicons of [two DAZ – two BPY2 – one CDY1] genes with no apparent effect on infertility status (Fisher’s exact test, p=0.34)." (PMID 33781384, 2021). "CDY1 will contribute to discover if full spermatogenesis is occurred or not and helps infertile men for sperm retrieval, until serum markers are emerged." (PMID 27525321, 2016). "As expected, CDY1 was expressed in infertile patients without AZFc deletion independently fromtheir collocation with or without the cluster, but not in patients with AZFc deletion." (PMID 20576090, 2010).
breast carcinoma (1 paper, 2013). "Conversely, within the same cell lines there is a substantial decrease in the HATs GTF3C4 (H3K14ac), MYST1 (H4K16ac) and CDY1 (H4ac), and this is consistent with the observed decrease in H4 acetylation in the MCF7 and MDA-MB231 breast cancer cell lines." (PMID 23826629, 2013).
cervical cancer (1 paper, 2023). A primary or metastatic malignant neoplasm involving the cervix. "In total, 28 genes (e.g., ATF2, BRCA2, CSRP2BP and EP300) were up-regulated and 16 genes (e.g., CDY1, CHAT and CRAT) were down-regulated in cervical cancer." (PMID 37845756, 2023).
CDY1 also shares sentences with these, for which no sentence is quoted: male infertility (2 papers); colon cancer (1); migraine (1); multiple myeloma (1).